CXCL10 (C-X-C motif chemokine ligand 10)
Diseases named in the same sentence as CXCL10 in open-access papers (continued):
Sharing a sentence is not in itself a finding about the gene and the disease.
tumor (continued). "The observation that TLR3 is expressed in the plasma membrane of metastatic epithelial cells and that TLR3-dependent CXCL10 induction can occur in response to extracellular stimuli suggests that malignant TLR3-expressing IECs could potentially respond to TLR3 ligands in the tumor microenvironment." (PMID 28717003, 2017). "Recently, studies have shown that CD103+ CD11c+ DCs, a subpopulation of dermal- and gut-resident pAPCs, respond to tumor-derived CCL4 and are the chief cells that produce CXCL9 and CXCL10 to recruit tumor-infiltrating T cells." (PMID 29109732, 2017). "We performed cell experiment on CXCL10, whose gene expression reached the lowest after 48 hours transfection, and its inhibition can effectively restrain OSCC tumor proliferation and metastasis." (PMID 28176846, 2017). "RT can also facilitate the recruitment of effector T-cells to the tumor by inducing the secretion of CXC motif chemokine ligand CXCL9, CXCL10 and CXCL16 by tumor cells." (PMID 29100279, 2017). "Further contributing to the tumor suppressing function of Th17 cells is the production of the chemokines CXCL9 and CXCL10, which facilitates the recruitment of CD8+ T cells into the tumor." (PMID 28938918, 2017). "In 20 Ewing sarcoma patients, Berghuis reported that CXCL9, CXCL10, and CCL5 that is highly expressed by tumor and stromal cells were correlated positively with accumulated CD8+ T cells." (PMID 27726306, 2016). "In our study we evaluated the effect of CXCL10 via neutralization, which demonstrated that CXCL10 played a significant role in MSC-Sirt1-induced tumor suppression in vivo." (PMID 27782173, 2016). "Meanwhile, in breast cancer, CXCL10/CXCR3 axis presented with tumor infiltrating lymphocytes (TILs), tumor progression and invasion, and poor prognosis." (PMID 26910919, 2016). "Interferon-gamma induced protein 10 (IP10), also known as CXCL10, induces the migration of immune cells towards tumours via chemotaxis mediated by CXCR3 receptor interactions." (PMID 27117228, 2016). "To analyze the mechanism by which MSCs-Sirt1 recruit NK cells for tumor inhibition, we measured the serum levels of chemokines CXCL9, CXCL10, and CXCL11." (PMID 27764779, 2016). "CEBPB shares functional interactions with CXCL10/IP-10, and both CEBPB and CEBPD are known to be tumor suppressors." (PMID 27764787, 2016). "The aberrant STAT3 signaling in tumor cells can suppress the expression of pro-inflammatory danger signals (e.g., IFNγ, TNF, CXCL10), while induces the expression of immunosuppressive factors (e.g., VEGF, IL-10) that inhibit DCs maturation." (PMID 27917371, 2016). "HPV-positive tumor tissue-derived cell cultures produced much higher levels of chemokines, namely CXCL9, CXCL10, CXCL12, CCL17 and CCL21." (PMID 25949860, 2015). "In murine tumor models, IL21 induces a Th1 immune response and anti-angiogenic effects mediated by CXCL9 and CXCL10." (PMID 26305332, 2015). "As expected, the migration of CD8+ T lymphocytes induced by tumor supernatant was partially but significantly inhibited by CCL5- and/or CXCL10-neutralizing antibodies." (PMID 26317795, 2015). "Meanwhile, RT-PCR data showed that the expression of CCL5 and CXCL10 was positively correlated with the local expressions of the CD8+ T lymphocyte markers (CD8 and Granzyme B) in tumor tissues." (PMID 26317795, 2015). "IFN-γ enhances antigen presentation by dendritic cells and stimulates production of the CXC chemokines MIG (CXCL9) and IP-10 (CXCL-10), which inhibit tumor angiogenesis and recruit CXCR3-bearing effector cells to tumor sites." (PMID 26458364, 2015). "Mouse (host) microarray analysis showed a significant increase in the NK cell damage response receptor CXCR3, which binds tumor-cell specific membrane-bound activation ligands CXCL9, CXCL10, and CXCL11, all of which were also increased on the human array." (PMID 25952672, 2015).
tumor (continued). "Although expression of CCL5, CXCL9, CXCL10 and CXCL12 were also consistently detected in the tumours, expression of each was also detected in spleen and lymph node." (PMID 25495686, 2015). "Accordingly, we have demonstrated that TLR3 triggering can directly induce the apoptosis of TLR3-expressing tumor cells, and the expression of chemokine CXCL10 and CCL5 which promote infiltration of T cells and NK cells into the tumor." (PMID 26287667, 2015). "HPV-positive tumor tissue-derived cell cultures produced markedly higher levels of chemokines, namely CXCL9, CXCL10, CXCL12, CCL17 and CCL21, and slightly higher levels of the cytokines IL-2, IL-17, IL-23 and IFNγ." (PMID 25949860, 2015). "CXCL9, CXCL10, CXCL12 and FSP1 production by CAFs promote recruitment of T lymphocytes into the tumor; however the number of cytotoxic T cells versus tumor suppressive cells is shifted." (PMID 24978438, 2014). "CCL21 mediated immune response included an increased influx of CD4 and CD8 T cells and DC in the tumor, as well as increased IFN-γ, MIG-CXCL9, CXCL10, GM-CSCF and IL-12, but a concomitant decrease in immunosuppressive molecules such as PGE-2 and TGF-β." (PMID 24810425, 2014). "CXCL10 was shown to promote the secretion or activity of MMPs in CRC cells and monocytes, thus enhancing the malignancy of the tumour microenvironment." (PMID 24748971, 2014). "A different group of researchers has attempted retroviral introduction of the CXCL10 gene into DCs and observed improved CD8+ T cell response and tumor rejection." (PMID 24967094, 2013). "This was shortly followed by the increase of tumor antigen specific CD8 T cells and their migration to tumor sites due to chemokines such as CCL2 and CXCL10 that were released by the activated APCs." (PMID 23555875, 2013). "In our study, preferential homing of Th1 CD4 T cells to intracranially implanted tumours correlated with high expression of CXCR3, which is a receptor for IFN-γ-inducible protein (IP)-10/CXCL10." (PMID 23717511, 2013). "The anti-angiogenic (CXCL9, CXCL10) and pro-angiogenic markers (VEGFa, CXCL2, CXCL5, Angiopoietin 1 and Angiopoietin 2) were quantified in the tumor by RTQPCR." (PMID 22815789, 2012). "Although CXCR3 is expressed in cytotoxic T cells, several studies demonstrated that CXCL9 and CXCL10 induced migration of CXCR3+ tumor cells, suggesting that CXCR3+ tumor cells preferentially metastasize to lymph nodes expressing these ligands." (PMID 24213462, 2012). "RNA and protein levels of two known ligands of CXCR3, CXCL10/IP10 and CXCL11/IP9 were down-regulated in the tumor lines." (PMID 22236567, 2012). "Chemokines that are found in the tumour environment, produced mainly by activated macrophages, are the CXCR3 ligands CXCL9/MIG and CXCL10/IP-10, attracting CXCR3-expressing T-cells and natural killer cells." (PMID 21179030, 2011). "Intrahepatic lymphocytes, isolated from non-tumor tissue, were stimulated with peptides overnight and culture supernatants were screened for CXCL-8, CXCL-9, CXCL-10, CCL-5, CCL-2 as well as IL-17 and the anti-inflammatory cytokine IL-10." (PMID 21876747, 2011). "Tumour endothelial cells demonstrated a more than 11-fold increase in CXCL9 mRNA expression and a 3- to 20-fold increase in CXCL10 mRNA expression, as compared with BECs or LECs in all samples." (PMID 21179030, 2011). "By day 7, IFNγ, CSF2, CXCL10, GZMB, PTGS2, TNFα, CD80, CCL22, IL12a, IL13, IL1b, IL6, NOS2, and CTLA4 were significantly upregulated in the tumor-bearing mice bladders and AGTR2 and GATA3 were downregulated." (PMID 22013484, 2011). "In contrast, EpCAM, IL8, CXCL10/IP10, CCL3/MIP-1α, CCL4/MIP-1β, CCL15/MIP-1δ, PDGFR-B were predominantly elevated in tumours compared to AN and PN." (PMID 21092330, 2010). "For the tumor stroma, a five gene classifier consisting of probesets for PSPHL (205048_s_at), CXCL10 (204533_at), CXCL11 (211122_s_at), ISG20 (204698_at), and GMDS (204875_s_at) was identified." (PMID 19225562, 2009).
tumor (continued). "Examples of those included PSPHL, TMPO, CRYBB2, and AMFR in the tumor epithelium and PSPHL, CXCL10 and CXCL11 in the tumor stroma." (PMID 19225562, 2009). "The tumour sites of CCL19-treated mice revealed significant increases in IFN-γ, CXCL10/CXCL10/IP-10, CXCL9/CXCL9/MIG, and GM-CSF." (PMID 16598185, 2006). "Compared to diluent-treated controls, the treatment group receiving CCL19 had a significant increase in type 1 cytokines (GM-CSF, IFN-γ) and antiangiogenic chemokines (CXCL9, CXCL10) and a decrease in the immunosuppressive cytokine TGF-β at the tumour sites." (PMID 16598185, 2006). "This study integrates single-cell RNA sequencing (scRNA-seq) of NPC tissues with validation in 109 primary patient samples, revealing CXCL10 and CCL20 as tumor-secreted chemokines localized to distinct malignant epithelial subpopulations with antagonistic roles." (PMID 41399390, 2026). "In contrast, M1-like macrophages could produce CXCL9 and CXCL10, activating effector CD8+ T cells, thereby enhancing anti-tumor immunity." (PMID 41635851, 2026). "In summary, we found that CXCL10 and CCL20 in NPC primarily originate from tumor cells and may represent a pair of antagonistic cytokines." (PMID 41399390, 2026). "Mechanistically, tumor DNA released by cryoablation was taken up by macrophages, activating the cGAS-STING signaling pathway, increasing the pool of CXCL10+ macrophages and CXCL10 secretion." (PMID 41818612, 2026). "Combinatorial therapy regimens combining CXCL10-targeted agents with ICIs, JAK/STAT inhibitors or PI3K/Akt pathway modulators should also be investigated in clinical trials, especially in resistant or immune-excluded tumor types." (PMID 40760734, 2025). "For instance, tumour cells with high FAT2 expression have been reported to upregulate several chemokines that influence immune cell behaviour, including CCL2, CCL3, CCL4, CCL19, CXCL10, and CXCL11." (PMID 40361472, 2025). "Innate immune cells, such as mature dendritic cells (mDCs) and M1-like tumor-associated macrophages (TAMs), secrete cytokines, such as IFN-α, IL-12, IL-18, and TNF, along with chemokines like CXCL9, CXCL10, and CCL21, which effectively suppress tumor angiogenesis." (PMID 40322886, 2025). "However, through its interaction with TLR4 on these cells, local CXCL10 can drive their reprogramming toward a pro-inflammatory, anti-tumoral M1 phenotype, thereby shifting the TME from a state that supports tumor growth to one that actively suppresses it." (PMID 41516196, 2025). "Therapeutic targeting of the CXCL10 and MAPK/ERK signaling pathways has gained ‎‎attention in cancer therapy as they play a central role in cancer progression, immune ‎modulation ‎and regulation of the tumor microenvironment." (PMID 40760734, 2025). "Given the inverse relationship between CCL23 and CXCL10 in human ovarian ascites samples and reduced survival in patients with low tumor CXCL10 expression, we hypothesized that the activation of CCR1 via CCL23 impairs CXCL10 secretion from myeloid cells." (PMID 41463176, 2025). "By increasing the local concentration and activity of CXCL10 within the TME, it may be possible to convert this immune desert into a hotbed of anti-tumor activity." (PMID 41516196, 2025). "CXCL10 binds to its receptor CXCR3, thereby recruiting T cells to the tumor." (PMID 41463372, 2025). "Activation of the cGAS/STING pathway by PARPi-induced accumulation of double-stranded DNA fragments in the cytosol of tumour cells initiates a type I interferon-like response with the release of the T cell-recruiting chemokines CCL5 and CXCL10, but also the upregulation of PD-L1." (PMID 40579444, 2025). "CXCL10 predominantly targets T cells, and its interaction with the CXCR3 receptor on T-cell surfaces promotes its recruitment to tumor sites, thereby augmenting anti-tumor immunity." (PMID 41368644, 2025).
tumor (continued). "For patients identified early (e.g., with low to medium circulating CXCL10 and no overt metastases), a logical strategy is to disrupt the entire pro-tumor cycle." (PMID 41516196, 2025). "To clarify whether PRMT5 directly regulates the CXCL10/CXCR3 signaling pathway, we established tumor models in CXCR3 KO mice with control cells and PRMT5 knockdown U14 cells." (PMID 41463372, 2025). "Bridging chemotherapy is often used to control tumor progression during this period and has been shown to enhance CAR-T efficacy by reducing immune suppressor cells in the tumor microenvironment and upregulating chemokines such as CCL5, CXCL9, and CXCL10 to improve T cell trafficking." (PMID 40312353, 2025). "This combination therapy specifically activates the cGAS-STING signaling pathway and stabilizes the mRNA expression of the chemokine CXCL10 through an EIF4E2-dependent mechanism, thereby promoting T-cell infiltration into the tumor microenvironment and enhancing anti-tumor immune responses." (PMID 41367875, 2025). "Importantly, in Uba1-overexpressing tumors, we detected diminished surface expression of tumor-specific MHC-I and reduction of mRNA levels of Cxcl10, Cxcl9, and MHC-I genes compared with the control." (PMID 39540840, 2025). "Furthermore, type I IFN responses in tumor cells lead to the secretion of chemokines, such as CXC-chemokine ligand 10 (CXCL10), which promote immune cell recruitment." (PMID 40004078, 2025). "In the Oncology VascHT29 Combo ELECT system, Keytruda (50,000 ng/mL) also reversed the hsa/mtCXCL8-mediated inhibition of key adhesion molecules like VCAM-1, CXCL-10, CXCL-9, and CD69 at the highest dose, promoting immune cell adhesion and recruitment into the tumor site." (PMID 40124384, 2025). "Similarly, in tumor endothelial cells, STING activation triggers type I IFN production, which in turn stimulates CXCL10 secretion, facilitating T cell transendothelial migration." (PMID 41204180, 2025). "Olaparib promotes CD8+ T-cell infiltration via the cGAS/STING pathway, especially in BRCA1-deficient tumours, while increased cytosolic DNA leads to CCL5/CXCL10-driven T-cell recruitment, independent of BRCA status." (PMID 40361472, 2025). "The ligands CXCL9, CXCL10, and CXCL11 all bind to CXCR3 and are primarily secreted by immune cells such as leukocytes and macrophages, as well as by dendritic cells, fibroblasts, and tumor cells." (PMID 40362215, 2025). "Additionally, they promote an increase in M1 macrophage population rather than M2 phenotype while upregulating production of CXCL9 and CXCl10 by these macrophages, thereby facilitating infiltration of CD8+ killer T cells into the tumor microenvironment." (PMID 39958358, 2025). "On the other hand, in cancers where CXCL10 supports anti-tumor immunity, care must be taken not to attenuate positive immune activity." (PMID 40760734, 2025). "Rather than migrating to the primary tumor to execute their anti-cancer functions, these effector cells are re-routed toward the higher systemic and pulmonary CXCL10 concentration, effectively decoyed away from their intended targets." (PMID 41516196, 2025). "Interestingly, chemokines such as CXCL9, CXCL10 and CXCL13 are involved in fostering the hot tumour milieu." (PMID 40852716, 2025). "Single-cell RNA sequencing of tumor samples from patients with HCC (GSE189903) revealed that intratumoral PD-L1(+) TAMs were enriched for immune-related signaling pathways and expressed chemokines including CXCL9, CXCL10, and CXCL11." (PMID 41027276, 2025). "Furthermore, the SNHG26‐CDKN2A axis modulated the tumour immune microenvironment by regulating CD8+ T cell cytotoxicity and chemokine expression, specifically downregulating CXCL9 and CXCL10, which are critical for T cell recruitment." (PMID 41310877, 2025). "Therefore, CXCL10 plays a dual role in the TME by promoting either the antitumor immunosurveillance or immunosuppression and tumor progression, in function of the tumor type and specific TME characteristics." (PMID 40211394, 2025).
tumor (continued). "Furthermore, we found higher levels of CXCL10, IL-9, and CCL4 in cases with higher numbers of T cells in direct contact with tumor cells, and thus their potential targets, while in these cases, VEGF levels were reduced." (PMID 40497965, 2025). "Depletion of CXCL10 in stromal cells reduced metastasis without affecting primary tumor growth, highlighting its stroma-specific, pro-metastatic role." (PMID 40760734, 2025). "USP6 exhibits tumor-suppressive functions in Ewing sarcoma by enhancing immune activation and chemokine production (such as CXCL10 and CCL5), which could counteract tumor growth." (PMID 40348771, 2025). "Chemokines are key mediators of T-cell migration, but tumours frequently downregulate the expression of chemokines required for T-cell homing, such as CXCL9 and CXCL10, while upregulating signals that preferentially attract immunosuppressive cells, such as Tregs and MDSCs." (PMID 40624498, 2025). "Notably, VEGF-A (M0), CXCL10 (M1), and MCP-1 (M2), known cytokines that are expressed highly in the respective macrophage when they are educated by tumor cells, were identified." (PMID 40940877, 2025). "Key chemokines involved in CD8+ T cell recruitment (CCR3, CXCL10, CXCL9) and their receptors (CCR2, CCR5, CXCR3) were consistently downregulated in FAM174B-high tumors, potentially limiting effector immune cell trafficking to the tumor microenvironment." (PMID 40959568, 2025). "CXCL10, through its receptor CXCR3, plays a dual role in tumor immune escape." (PMID 41376630, 2025). "In certain cancers, ‎CXCL10/CXCR3 signaling via the PI3K/Akt pathway helps cancer cells evade immune surveillance, allowing them to evade apoptosis and promote angiogenesis, which in turn promotes tumor ‎survival and spread." (PMID 40760734, 2025). "Among them, the chemokine family, including CC (e.g., CCL1, CCL3, CCL5, CCL7, and CCL15), CXC (e.g., CXCL1, CXCL3, CXCL5, and CXCL10), XC (e.g., XCL1 and XCL2), and CX3C (e.g., CX3CL1), plays a pivotal role in tumor development, metastasis, and chemotherapy resistance 30-33." (PMID 40740234, 2025). "CXCL10, which binds to CXCR3 on activated T cells and promotes their directional trafficking, is a major factor driving the attraction of T cells to tumor sites." (PMID 40025520, 2025). "Up-regulation of CXCL10, in conjunction with a unique structural domain, Glu-Leu-Arg, within the protein, can have tumor suppressor and tissue repair roles rather than pro-inflammatory and tumorigenic roles." (PMID 40149853, 2025). "Mechanistically, ROS1-mutant tumors displayed an immunosuppressive tumor microenvironment characterized by diminished CD8+ T cell infiltration, attenuated interferon-γ signaling, and downregulation of immune-related genes (CXCL9, CXCL10, IFNG, PD-L1)." (PMID 40873541, 2025). "Our model reframes CXCL10 not merely as a biomarker but as a functional, systemic modulator of immune evasion, a process initiated by the primary OS tumor and its early communication with the PMN in the lungs." (PMID 41516196, 2025). "Additionally, in CMT-N7 cells, TNF/MAPK inflammatory pathway-related genes such as CXCL10 and MECOM were significantly upregulated following W6134 and XY018 treatment, exhibiting favorable anti-tumor effects, which aligns with previous findings." (PMID 40805064, 2025). "For example, L. paracasei sh2020 has shown a synergetic anti-tumor effect with anti-PD1 by enhancing the anti-tumor function and intestinal barrier function, which induces the up-regulation of CXCL10 expression in tumor and subsequently increases the recruitment of CD8+T cells." (PMID 40535013, 2025). "Notably, however, our data also illustrates a strong induction of TH1‐type chemokines CXCL9, CXCL10 and CXCL11, which are ligands for CXCR3 and critical to drive T‐cell recruitment to the tumour sites." (PMID 39743376, 2025).